IL1B (interleukin 1 beta)
Diseases named in the same sentence as IL1B in open-access papers (continued):
Sharing a sentence is not in itself a finding about the gene and the disease.
colitis (continued). "Pro-inflammatory cytokines, namely TNF-α, IL-1β, and IL-6, play pivotal roles in the inflammatory process, precipitating tissue damage and exacerbating colitis." (PMID 40077487, 2025). "Another recently developed BsAbs is FL-BsAb1/17, targeting IL-1β and IL-17A; it was compared to etanercept in a recent study, showing potential to become a new dual-target candidate for colitis treatment." (PMID 40001525, 2025). "Conversely, using the FLC functional blocker peptide F991 significantly reduces activated IL-1β, IL-18, and activated caspase-1, while alleviating colitis progression and decreasing tumorigenesis." (PMID 40806736, 2025). "Further, dietary administration of S. boulardii to mice with dextran sulfate sodium (DSS)-induced colitis improved colon injury and reduced inflammatory responses by modulating gene expression of proinflammatory cytokines, such as Tnfα, IL-6, and IL-1β." (PMID 40872558, 2025). "Administration of S. boulardii in rats with 2,4,6-trinitrobenzenesulfonic acid (TNBS)-induced colitis improved histological damage, diarrhea, and colonic gene expression of IL-1β, IL-6, and Tnfα." (PMID 40872558, 2025). "Inflammation of the colonic mucosa is a key feature of colitis, where the role of pro-inflammatory mediators such as IL-1β, IL-6, IL-23 and TNF-α is well established." (PMID 40943092, 2025). "Quercetin can also reduce the expression of TNF -α and IL-1β and alleviate the colitis in mice induced by DSS." (PMID 40699713, 2025). "Analysis of liver tissue from DSS-induced colitis mice revealed elevated production of pro-inflammatory cytokines, such as IL-1β, IL-6, and TNF-α, along with upregulated LPS and MPO levels." (PMID 40725052, 2025). "Studies have shown that different Lactobacillus strains that possess the hdc gene cluster can reduce colitis through histamine H2 receptor-mediated IL-1β and IL-6 reduction in distal small intestine and cecum of mice (79, –, 81)." (PMID 39902926, 2025). "Deferasirox pretreatment has been shown to reduce inflammation-related oxidative stress and IL-1β expression in mice with DSS-induced colitis." (PMID 40822452, 2025). "In a colitis model, neutrophil depletion led to a significant reduction in IL-1β expression in the colon, with neutrophil transfer being sufficient to restore IL-1β production, further emphasizing the critical role of neutrophils in IL-1β generation." (PMID 41087719, 2025). "DCL (5 and 10 μg/kg) markedly inhibited DSS‐induced increase of ASC puncta formation, IL‐1β and IL‐18 secretion in colons of colitis mice." (PMID 40919130, 2025). "The anti-inflammatory effect of probiotics has been confirmed TNF-a, IFN-γ, IL-10, and IL-1β in the DSS-induced colitis mouse model." (PMID 40219015, 2025). "Findings from previous investigations have shown that the intestinal mucosal barrier was disrupted in rats with experimental colitis when inflammatory factors (such as IL-6, IL-8, IL-1β, and TNF-α) were elevated, leading to intestinal barrier dysfunction." (PMID 40129987, 2025). "Reduced hepatocyte swelling in mice with colitis, inhibited IL-1β and TNF-α expression, and attenuated hepatic inflammation and cholestasis by regulating TLR4 NF-κB and bile acid metabolic pathways." (PMID 40066456, 2025). "Studies have shown that DSS-induced colitis in mice results in increased levels of IL-6 and IL-1β, consistent with the findings of this study." (PMID 40431130, 2025). "This interaction initiates caspase recruitment domain-containing protein 9 (CARD9)-dependent nuclear factor kappa-B (NF-κB) activation, leading to the production of IL-1β, a cytokine critical for protection against colitis." (PMID 40284630, 2025). "Modulating the Treg/Th2 response by decreasing proinflammatory cytokines such as TNFα, IL-6, IL-1β, IL-18, IL-22, IL-9 and increasing anti-inflammatory cytokines IL-10 and IL-4 in mice colitis model." (PMID 41208998, 2025).
colitis (continued). "Meanwhile, ELISA analysis showed that 4-OI treatment significantly reduced levels of pro-inflammatory cytokines (IL-1β and IL-6) in both colitis tissues and serum." (PMID 41417165, 2025). "In a Salmonella-induced colitis model, BB-12 was shown to alleviate inflammation by modulating the relative expression of the colonic cytokines IL-1β, TNF-α and CXCL2, and reducing the secretion of IL-1β, IL-6, and TNF-α in serum and colonic tissues." (PMID 40673154, 2025). "In both acute and chronic colitis models, vehicle-treated mice showed a significant increase in pro-inflammatory cytokines, IL-6, IL-1β, MCP-1, and TNF-α, compared to healthy controls, which was markedly attenuated by the combination therapies." (PMID 40869234, 2025). "The molecular mechanisms elucidated in this study suggest a multi-faceted approach, wherein Homo suppresses the expression of pro-inflammatory cytokines including, TNF-α, IL-1β, and IL-6, which are critical mediators in the pathogenesis of colitis." (PMID 40529132, 2025). "Correspondingly, IL-1β production was markedly reduced in the colon of rPrdx1-treated colitis mice following MCC950 administration." (PMID 40715057, 2025). "In vivo, administration of an IL-18BP alleviated DSS-induced colitis and single knockout of IL-18 (as well as double knockout together with IL-1β) protected against dinitrobenzene sulfonic acid (DNBS)-induced colitis." (PMID 40869366, 2025). "They showed that a low dose of IL-1β administered 24 h before dextran sulfate sodium (DSS) exposure protected against colitis, whereas administration just 30 min prior to DSS initiation did not confer protection." (PMID 40869366, 2025). "Galectin-3 enhances NOD-like receptor family pyrin domain containing 3 (NLRP3) inflammasome activity, leading to elevated secretion of interleukin-1 beta (IL-1β) and IL-18, as shown in colitis and hepatobiliary inflammation models." (PMID 40806347, 2025). "In this study, TNF-α, IL-1β and IL-6 levels were higher unsupplemented colitis-affected rats compared to healthy rats." (PMID 41515203, 2025). "Studies on colitis have demonstrated that resting peritoneal macrophages from SUCNR1-deficient mice secrete less pro-inflammatory factors IL-1β, IL-6 and TNF-α and, thus, exert a protective effect against colitis." (PMID 40243444, 2025). "Findings from this study indicate that DSS-induced colitis in rats leads to significantly increased levels of IL-1β, IL-6, TNF-α, and MDA, along with a notable decrease in SOD levels, suggesting severe oxidative damage and inflammatory responses." (PMID 40417008, 2025). "In contrast, DSS-induced colitis mice that received TcES exhibited significant decreases in the production of TNF-α, IL-1β, and IL-33, as well as Th17-associated cytokines such as IL-23 and IL-17F." (PMID 40576745, 2025). "Mice with colitis exhibited increased expression of inflammatory markers, Il‐1β, c‐Jun, and NF‐κB p65 in their kidneys." (PMID 40018982, 2025). "This consequently suppresses pro-inflammatory cytokines (IL-1β and IL-6), alleviates colitis, and enhances gut barrier function." (PMID 41010521, 2025). "Kidney weight and kidney Il‐1β correlated with the main markers of colitis, e.g., and histopathological scores, colon length, fecal albumin." (PMID 40018982, 2025). "iTcES treatment resulted in a significant reduction in TNF-α, IL-1β, IL-23, IL-17F, and IL-33 levels; all of these cytokines are known to exacerbate colitis by promoting intestinal epithelial cell death and disrupting the epithelial barrier." (PMID 40576745, 2025). "Glycyrrhiza chalcone inhibited TNF-α, IL-1β, and IL-6 expressions in the colon tissue of mice with colitis." (PMID 41180229, 2025). "Regarding IL-18, sanguinarine relives colitis by inactivating NLRP3-Caspase1/IL-1β pathway, which in turn upregulates IL-18 to exert proinflammatory effects." (PMID 40092732, 2025).
colitis (continued). "We also confirmed that IL-1b protein was upregulated in DSS colitis and attenuated in Cth–/– mice, which we demonstrated by both ELISA and IHC." (PMID 39427081, 2024). "And it is reported that Staphylococcaceae has a significant positive correlation with the expression of intestinal pro-inflammatory cytokines such as IL-1b in a colitis model." (PMID 39081865, 2024). "DCs exhibited the lowest M1 and M2 scores, while mono- and inflammatory macrophages displayed higher M1 scores, indicating the dominance of pro-inflammatory macrophages during colitis (related to Il1b, Irf1, Cd14, Fcgr3 expression level)." (PMID 38674054, 2024). "Previous studies have shown that IL-1β has a protective role during chemical-induced colitis, by driving epithelial repair following injury." (PMID 38236896, 2024). "The expression of NLRP3, ASC and caspase-1 was significantly increased in a DSS-induced mouse colitis model, resulting in activation of related proteins and increases in the levels of IL-18 and IL-1β." (PMID 39517291, 2024). "More importantly, mice deficient for IL-10 have been shown to display elevated inflammasome activation and IL-1β production resulting in severe colitis or Ag-induced arthritis." (PMID 38372712, 2024). "An increase in the relative abundance of Terrisporobacter and Turicibacter has been shown to positively correlate with the mRNA expression of pro-inflammatory factors (IL-1β), which in turn induce the development of colitis in mice." (PMID 38671889, 2024). "NK109 also suppressed the LPS-induced expression of colonic myeloperoxidase, TNF-α, and IL-1β expression, resulting in the attenuation of colitis." (PMID 39203872, 2024). "To further elucidate the anti-inflammatory effects of HU308 in DSS-induced colitis, we measured the levels of several pro-inflammatory cytokines in chronic colon tissues, including IL-6, IL-1β, IL-17, MCP-1, TNF-α, and IFN-γ." (PMID 39682761, 2024). "FcγR-KO mice inoculated with ASCA displayed a significantly reduced susceptibility to colitis, with decreased DAI values compared to WT mice and lower levels of IL-1β in the supernatants of colonic explants." (PMID 39080486, 2024). "The levels of the inflammatory factors IL-1β, IL-6, and TNFα in mouse intestinal tissue were studied to evaluate the extent of colitis-related inflammation." (PMID 39250508, 2024). "Of the inflammatory mediators, we found IL-1β as a central molecule in a single cycle of the DSS-induced colitis model." (PMID 38491049, 2024). "The reduced severity of colitis in MC-170073-treated mice given DSS was also associated with lower levels of both colonic MPO and the proinflammatory cytokines IL-1β, IL-6, and TNF-α." (PMID 38713616, 2024). "There is growing evidence that the proinflammatory cytokines IL-6 and IL-1β play a crucial part in the uncontrolled colitis process." (PMID 38998493, 2024). "The changes in the expression of inflammasome component genes (NLRP3, caspase-1, ASC) and IL-1β in the colon tissue of DSS-induced colitis mice following EIF treatment were examined using RT-qPCR." (PMID 39408295, 2024). "Studies have shown that patients with colitis exhibit upregulated IL-1β expression along with an increase in Allobaculum and Bifidobacterium as well as a decrease in Lactobacillus within the gut." (PMID 39078497, 2024). "For instance, in an acetic acid-induced colitis rat model, ghrelin was shown to downregulate key inflammatory factors, such as IL-1β, TNF-α, and myeloperoxidase, providing a protective effect." (PMID 38275675, 2024). "For example, the active extract of ginseng (a plant used in traditional Chinese medicine) has been shown to reduce colitis symptoms by decreasing the levels of IL-1β and TNFα and promoting M2 macrophage polarization." (PMID 38892549, 2024). "When compared to control colitis animals, the expressions of inflammatory markers such as IL-1β, IL-4, IL-6, and Cxcl2 were significantly lower in mice receiving IAA treatment." (PMID 39068517, 2024).
colitis (continued). "TNF-α, IL-1b, and IL-6 have been shown to promote colonic inflammation, with TNF-α causing damage to the intestinal mechanical barrier, and IL-10 and IL-12, which are anti-inflammatory cytokines, which can inhibit inflammation." (PMID 39723143, 2024). "The absence of AIM2 affected caspase-1 activation and the production of IL-1β and IL-18, whilst also making mice highly susceptible to DSS-induced colitis associated with microbial dysbiosis." (PMID 39684769, 2024). "IL-10 is able to suppress T cell-mediated immune response and ameliorate colitis by inhibiting antigen presenting cells, and downregulate IL-1β, IL-6, and TNF-α secreted by macrophages and T cells." (PMID 38397562, 2024). "UD extract was found effective in reducing colitis clinical signs, as revealed by the significant reduction in inflammatory markers IL-1β and TNF-α in treated animals." (PMID 39000608, 2024). "An increasing body of studies has demonstrated that a notable elevation in proinflammatory cytokines, such as IL-6, TNF-α, and IL-1β, constitutes the primary characteristic of colonic injury during the course of colitis development." (PMID 39594091, 2024). "Here, we evaluated the effects of Raf on inflammation using a DSS-induced colitis mouse model, focusing on serum levels of IL-2, IL-1β, TNF-α, and IL-6." (PMID 38928791, 2024). "The excessive production of IL-1β has been shown to be involved in the development of inflammation and colitis." (PMID 39125598, 2024). "IL1β was demonstrated to be elevated in inflamed colon tissue, which in this study was experimental colitis, and when IL1β was injected to control animals, it dose-dependently enhanced thrombus formation." (PMID 39519000, 2024). "We also observed increased levels of inflammatory cytokines TNF-α, IL-1β, and IL-6 in two colitis groups." (PMID 39118149, 2024). "In a model of obese colitis mice, pectin administration increased the ratio between Bacteroidetes and Firmicutes, reducing the secretion of IL-1β and IL-6, with the attenuation of colitis." (PMID 39061865, 2024). "Most research on colitis focuses on the pro-inflammatory biomarker IL-1β, which is largely generated by lamina propria monocytes and macrophages that infiltrate the colitis mucosa." (PMID 38613080, 2024). "The NLRP1 inflammasome also plays a protective role in the development of colitis-associated CRC, which is associated with the release of the effector cytokines IL-1β and IL-18." (PMID 39684769, 2024). "Colitis is a chronic inflammatory digestive condition of the colon’s inner lining, commonly recognized by measurement of fecal IL-1β and mucosal TNF-α." (PMID 39000608, 2024). "In IBD, miR-223 inhibited NLRP3 expression and reduced IL-1β production, ameliorating colitis in a mouse model." (PMID 39684769, 2024). "In parallel, the phosphorylation of NF-κB p65 and IκBα (inhibitor of NF-κB) was decreased following the administration of over-expressed miR-146a EVs, leading to inhibited secretion of TNF-α, IL-6 and IL-1β and thus ameliorated colitis." (PMID 38323035, 2024). "Further, the NLRP3-mediated inflammasome activity was inhibited based on results showed that DCA was able to reduce expression level of cleaved caspase-1 and inhibit the activation of IL-1β in colitis-induced mouse model." (PMID 37902927, 2024). "FICZ provides protection against colitis by reducing the production of pro-inflammatory cytokines such as IL-17, IL-1β, IL-6, TNF-α, and IFN-γ, while promoting anti-inflammatory IL-22 production from Th17 cells." (PMID 39767818, 2024). "Exposed IS caused colitis in mice, decreasing colon length and IL-10 levels and increasing myeloperoxidase, TNF-α, IL-1β, and IL-6 levels in the colon." (PMID 39519543, 2024). "To confirm pyroptosis in a single cycle of DSS-induced colitis, we further examined the protein markers for pyroptosis (i.e., IL-1β and caspase-1), and found the expected changes in IL-1β and caspase-1 levels." (PMID 38491049, 2024).
colitis (continued). "The downregulated expressions of inflammatory cytokines such as TNF-α and IL-1β were noticed to recover the colonic ZO-1 protein abundance in the colitis mice." (PMID 39616350, 2024). "In dextran sulphate sodium-induced colitis mice, magnolol ameliorated disease activities index and suppressed expression levels of IL-1β, IL-12, and TNF-α via the regulation of NF-κB and peroxisome proliferator-activated receptor-γ pathways." (PMID 38541664, 2024). "It has been found that polyphenols from medicinal plants reduce DSS-induced colitis symptoms by decreasing inflammatory cytokines, such as IL-1β and IL-6, together with antioxidant capacity." (PMID 38892549, 2024). "It is established that TNF‐α, IL‐6, and IL‐1β are key proinflammatory cytokines involved in the onset of colitis, and IL‐10, an anti‐inflammatory cytokine, increases following Res administration in IBD patients." (PMID 38372468, 2024). "It was similarly found that the concentration of IL-1β in mice was elevated and the colonic mucosa was severely damaged after we induced colitis in miR-30c KO mice with DSS." (PMID 38342939, 2024). "Treatment with MV significantly reduced the releases of proinflammatory factors TNF-α, IL-1β, and increased the levels of anti-inflammatory factors IL-2 in mice with colitis, indicating its good anti-inflammatory effects." (PMID 38773576, 2024). "Coumaric acid modulated the expression of inflammatory markers, including NF-κB, TNF-α, iNOS, IL-1β, and IL-6, in the colon during acetic acid-induced colitis." (PMID 38732594, 2024). "Pro-inflammatory factors such as IL-6 and IL-1β are the cytokines that mediate the pathogenesis of colitis." (PMID 39473926, 2024). "Huangqin Decoction significantly alleviated colitis in mice, reducing body weight loss, disease activity, colon shortening, tissue damage, and levels of TNF-a, IL-6, IL-1β, and COX-2 induced by DSS treatment." (PMID 39411430, 2024). "RT-qPCR analysis results showed that EIF treatment significantly reduced the expression of inflammasome component genes (NLRP3, caspase-1, and ASC) and IL-1β in the colon tissue of DSS-induced colitis mice." (PMID 39408295, 2024). "In this study, animals with colitis induced by AA displayed a notable increase in the concentration of both IL-1β and TNF-α, assessed through ELISA and immunohistochemistry, as reported by others." (PMID 39199130, 2024). "Induced NLRP3 expression combined with increased IL-1β levels were found as the predominant features for the initiation of colitis in miR-223 KO mice." (PMID 38323035, 2024). "Compared to the levels in the normal group, the proinflammatory cytokines (e.g., IFN-γ, TNF-α, IL-17A, IL-1β and IL-6) were significantly elevated in the colitis group, suggesting that mice bearing colitis have an increase in proinflammatory cytokines." (PMID 38396052, 2024). "first reported that ginsenoside Rg1 was capable of protecting against DSS-induced mouse colitis through markedly downregulating proinflammatory cytokines secretion (IL-1β and TNF-α)." (PMID 38698858, 2024). "On the contrary, the study conducted by Siegmund and co-workers reported that a caspase-1 deficit in DSS-induced colitis mice had protective effects on the evolution of the disease, related to the limited production of IL-1β and IL-18." (PMID 39684769, 2024). "boulardii combination (109 CFU/ml and 107 CFU/ml) significantly reduced the DAI, inhibited colitis, lowered IL-1β and TNF-α production, and significantly improved the levels of butyric acid and isobutyric acid." (PMID 38835484, 2024). "In this study, inflammasome-associated factors, including p-STAT3, NLRP3, IL-1β, and caspase-1, were significantly enhanced in a DSS-induced mouse colitis model." (PMID 39329121, 2024). "Targeting and blockade of IL-1β by genetic and pharmacological procedures in colitis mice resulted in attenuated colitis." (PMID 38323035, 2024).